NSUN2 (NOP2/Sun RNA methyltransferase 2)
Diseases named in the same sentence as NSUN2 in open-access papers (continued):
Sharing a sentence is not in itself a finding about the gene and the disease.
triple-negative breast carcinoma (3 papers, 2022 to 2025). An invasive breast carcinoma which is negative for expression of estrogen receptor (ER), progesterone receptor (PR), and human epidermal growth factor receptor 2 (HER2). "In triple-negative breast cancer, overexpression of NSUN2 promotes cancer cell proliferation, migration, and invasion through Myc." (PMID 40370440, 2025). "In triple-negative breast cancer (TNBC), changes in the expression of m5C RNA methylation regulators, with upregulation of NSUN2 and downregulation of NSUN6, can significantly predict clinical prognosis risk in TNBC patients." (PMID 40370440, 2025). "In triple-negative breast cancer (TNBC), upregulated NSUN2 acts as an oncogenic factor, while downregulated NSUN6 functions as a tumor suppressor." (PMID 40370440, 2025). "In triple-negative breast cancer (TNBC), NSUN2 expression is upregulated thereby acting as a tumor-promoting factor, whereas NSUN6 is downregulated as a tumor suppressor." (PMID 35562754, 2022). "As these are m5C methyltransferases of mRNA, correlations between NSUN2 and NSUN6 have been analyzed using bioinformatics, which have shown them to be positively correlated, uncorrelated and negatively correlated in renal cancer, triple-negative breast cancer, and cutaneous melanoma, respectively." (PMID 35562754, 2022).
abdominal aortic aneurysm (2 papers, 2023 to 2025). Enlargement and ballooning of the vessel that supplies arterial blood to the abdomen, pelvis and legs. "NSUN2 and NSUN5 were upregulated at both the protein and mRNA level in abdominal aortic aneurysm tissues." (PMID 41462962, 2025).
alopecia (2 papers, 2019 to 2022). Hair loss usually from the scalp. "Previous studies reported that Nsun2-KO male mice showed phenotypes, including weight loss, partial alopecia, and meiosis abnormality." (PMID 35743028, 2022). "The knockout (KO) of Nsun2 causes weight loss, partial alopecia, and meiosis abnormality in male mice." (PMID 35743028, 2022). "It has been shown that the loss of Nsun2 could cause several apparent phenotypes in male mice, including weight loss, partial alopecia, and meiosis abnormality." (PMID 35743028, 2022). "NSUN2 knock-out mice are viable, but appreciably smaller than their wild-type and heterozygous littermates, with males being sterile and both genders showing cyclic alopecia and brain development disorders." (PMID 31276587, 2019).
Anxiety (2 papers, 2014 to 2021). Intense feelings of nervousness, tension, or panic often arise in response to interpersonal stresses. "Together, these tests indicate that loss of NSun2 altered motor coordination or balance and reduced adaptive anxiety related behaviours in a novel environment." (PMID 25063673, 2014). "Furthermore, Nsun2 robustly shapes affective states associated with depression and anxiety." (PMID 34389722, 2021). "We were highly surprised to observe reductions in depression and anxiety-related behaviors in mice with neuronal Nsun2-deficiency, and we then wondered whether a viral-mediated increase in neuronal Nsun2 expression in the adult cortex would elicit similar or opposite phenotypes." (PMID 34389722, 2021). "Bi-directional changes in Nsun2 tRNA methyltransferase activity in adult PFC neurons are associated with directly opposing changes in behavioral despair paradigms and differential effects on anxiety-related behaviors." (PMID 34389722, 2021).
autism (2 papers, 2022 to 2025). Persistent deficits in social interaction and communication and interaction as well as a markedly restricted repertoire of activity and interest as well as repetitive patterns of behavior. "Our patient is a 15-year-old male with a history of autism, developmental delay, and focal epilepsy who underwent genetic testing and was found to have a homozygous frameshift mutation in NSUN2 predicted to cause loss of function." (PMID 36420349, 2022).
colorectal tumour (2 papers, 2024 to 2026). "Histopathological analysis showed advanced colorectal tumour stages in Nsun2+/+ mice compared with Nsun2‐/‐ mice, indicating the critical role of NSUN2 in the tumourigenicity and progression of CRC." (PMID 38468490, 2024).
gynecological cancer (2 papers, 2022 to 2024). "We primarily evaluated the role of NSUN2 in gynecological cancers through collecting the gene expression profile from multiple databases and websites including the GEO database, UALCAN website, oncomine, cBioPortal, and Kaplan–Meier Plotter." (PMID 35280737, 2022).
head and neck carcinoma (2 papers, 2020). A carcinoma that arises from the head and neck region. "Regarding tRNAs, NSUN2 overexpression indicates a shorter overall survival in head and neck carcinomas." (PMID 32241281, 2020). "High expression of NSUN2 has been reported to predict poor survival in head and neck cancer." (PMID 33365328, 2020). "Also, high levels of NSUN2 expression were detected in head and neck carcinoma." (PMID 32241281, 2020).
hypopharyngeal squamous cell carcinoma (2 papers, 2023 to 2025). "In addition, NSUN2 promotes hypopharyngeal squamous cell carcinoma (HPSCC) by m5C-methylating oncogenic TEAD1 (TEA domain transcription factor 1) mRNA, which upregulates its expression level." (PMID 37325635, 2023).
melanoma (2 papers, 2025). A malignant, usually aggressive tumor composed of atypical, neoplastic melanocytes. "Vitamin D3 significantly and specifically inhibited melanoma B16 cell proliferation and migration, enhanced vitamin D receptor expression, and reduced NSUN2 expression in melanoma cells." (PMID 41462962, 2025). "Overall, vitamin D3 inhibited the malignant progression of melanoma cells by binding to vitamin D responsive elements located upstream of the NSUN2 promoter, reducing the transcriptional activity of NSUN2." (PMID 41462962, 2025).
Obesity (2 papers, 2023 to 2025). Accumulation of substantial excess body fat. "In line with this, we observed lower NSUN2 gene expression post-surgery and among subjects with obesity across both adipose tissue depots." (PMID 41030849, 2025).
oral cancer (2 papers, 2020 to 2025). "A study revealed that NSUN2 gene copy number was elevated in colorectal and oral carcinoma.We also found that DCAF13 and BOP1 have high copy number gain frequency in patients with LUAD." (PMID 32071816, 2020).
oral cavity squamous cell carcinoma (2 papers, 2025). A squamous cell carcinoma arising from the oral cavity. "Although RNA modification has been widely discussed in cancer development and prognosis, the role of the NSUN2 gene in oral cavity squamous cell carcinoma (OCSCC) is unclear." (PMID 40657390, 2025).
thyroid cancer (2 papers, 2021 to 2023). "This study performed immunohistochemistry analysis to assess NSUN2 levels in thyroid cancer." (PMID 37983928, 2023). "Furthermore, the OncoPrint map of the NSUN2 gene of thyroid cancer patients in Memorial Sloan Kettering Cancer Center and The Cancer Genome Atlas (TCGA) datasets indicated <0.2% genetic alteration." (PMID 37983928, 2023).
type 2 diabetes mellitus (2 papers, 2025). A type of diabetes mellitus that is characterized by insulin resistance or desensitization and increased blood glucose levels. "In a study of the mechanism of 293T cells and type 2 diabetes mellitus, NSUN2 deficiency reduced ACSL6 expression by inhibiting m5C modification of ACSL6 mRNA." (PMID 41462962, 2025). "Overall, NSUN2 mediates the dysregulation of liver glucose and lipid metabolism during type 2 diabetes mellitus by relying on m5C-mediated ACSL6." (PMID 41462962, 2025). "NSUN2 is also significantly upregulated in liver tissues from type 2 diabetes mellitus (T2DM) patients and high-fat diet (HFD) mice." (PMID 41256859, 2025). "NSUN2 expression was significantly upregulated in clinical samples of type 2 diabetes mellitus and mice fed a high-fat diet." (PMID 41462962, 2025).
acute liver failure (1 paper, 2024). Rapid deterioration of liver function causing encephalopathy and coagulopathy. "Low NSUN2 expression was consistently observed in HBV patient samples with acute liver failure, indicating that HBV infection reduces NSUN2 expression in both cell culture and clinical samples." (PMID 38216565, 2024).
aneurysm (1 paper, 2023). Bulging or ballooning in an area of an artery secondary to arterial wall weakening. "NSUN2 influences autotaxin expression and T cell recruitment to control aneurysm development." (PMID 36911406, 2023).
Ataxia (1 paper, 2014). Ataxia refers to impaired coordination of voluntary muscle movement. "Depending on the mouse strain, homozygous deletion of NSun2 can be subviable and occasionally adult NSun2−/− mice show signs of ataxia (not shown)." (PMID 25063673, 2014).
autism spectrum disorder (1 paper, 2024). A spectrum of developmental disorders that includes autism, and Asperger syndrome. "NSUN2 can control the rate of protein synthesis through direct regulation of RNA methylation, and NSUN2-mediated m5C RNA methylation could be a promising treatment strategy for addressing the NMDAR system in individuals with autism spectrum disorders." (PMID 39344412, 2024).
autoimmune disease (1 paper, 2023). A disorder resulting from loss of function or tissue destruction of an organ or multiple organs, arising from humoral or cellular immune responses of the individual to their own tissue constituents. "Our study demonstrates a m5C mediated cell intrinsic function in Th17 cells and suggests Nsun2 as a potential therapeutic target for autoimmune disease." (PMID 36792629, 2023). "This unprecedented RoRγt-Nsun2 axis may become a potential valuable therapeutic target for clinical autoimmune disease." (PMID 36792629, 2023).
COVID-19 (1 paper, 2024). A disease caused by infection with severe acute respiratory syndrome coronavirus 2. "From our results, the NSUN2 expression level in patients with severe COVID-19 was lower than that in patients with mild COVID-19." (PMID 39110796, 2024). "We further collected BALF from patients with severe and mild COVID-19 with the SARS-CoV-2 Omicron subvariant BA.5.2 and found that NSUN2 expression levels and m5C levels decreased in patients with severe compared to mild COVID-19." (PMID 39110796, 2024). "When the patients recovered, the NSUN2 expression level in patients with COVID-19 returned to normal as in healthy people." (PMID 39110796, 2024). "NSUN2 mRNA levels were also reduced in patients with COVID-19 compared with healthy individuals." (PMID 39110796, 2024).
depression (1 paper, 2021). "Here, we report bi-directional changes in depression-related behaviors after genetic disruption of neuronal tRNA cytosine methylation, including conditional ablation and transgene-derived overexpression of Nsun2 in the mouse prefrontal cortex (PFC)." (PMID 34389722, 2021).
esophageal tumor (1 paper, 2021). "Histopathological analysis showed advanced esophageal tumor stages of Nsun2+/+ mice than those of Nsun2+/− mice." (PMID 34345012, 2021).
heart failure (1 paper, 2025). Inability of the heart to pump blood at an adequate rate to meet tissue metabolic requirements. "Cardiac-specific ablation of Nsun2 abolished the stress-induced heart hypertrophic response but exacerbated heart failure progression." (PMID 39990213, 2025). "Knockout of Nsun2 (αMHC-CreERT2, Nsun2 flox+/+) abolished the hypertrophic response of mice to diverse stresses, while accelerating the progression of heart failure." (PMID 39990213, 2025). "However, these remodeling alterations were abruptly halted by Nsun2 knockout, which exacerbated pressure overload-induced heart failure development." (PMID 39990213, 2025). "Upon deletion of Nsun2 (Nsun2 cKO) in the myocardium, these progressive alterations were nearly abolished or reversed except serum NT-proBNP levels that were significantly elevated, demonstrating suspended cardiac hypertrophy and acceleration of heart failure development." (PMID 39990213, 2025). "Myocardial depletion of Nsun2 compromises PKA signaling cascades and exacerbates heart failure progression under conditions of sustained pressure overload (Graphical abstract)." (PMID 39990213, 2025).
Hutchinson-Gilford progeria syndrome (1 paper, 2025). "Additionally, the expression levels of NSUN2 and NSUN6 were significantly decreased in a cellular model of Hutchinson-Gilford Progeria Syndrome (HGPS)." (PMID 40309035, 2025).
Infertility (1 paper, 2018). "Inhibition of global translation due to NSUN2 depletion halts the progression of a germ cell through the late stages of spermatogenesis, engendering infertility." (PMID 30697227, 2018). "Consequently, NSUN2 KO males not only have defect in hair growth but they also display infertility." (PMID 30697227, 2018).
injury (1 paper, 2025). Damage inflicted on the body as the direct or indirect result of an external force, with or without disruption of structural continuity. "Hence, NSUN2 expression and m5C levels were significantly increased in the traumatic brain injury model, with strong colocalization with glial fibrillary acidic protein." (PMID 41462962, 2025). "In vivo validation demonstrated that NSUN2 promoted A1 astrocyte activation through PTPRD, exacerbating traumatic brain injury-induced brain damage." (PMID 41462962, 2025). "NSUN2 enhances the m5C methylation stability of PTPRD mRNA, exacerbating A1 astrocyte activation and the subsequent inflammation-mediated tissue damage after traumatic brain injury." (PMID 41462962, 2025).
intellectual disability syndrome (1 paper, 2024). "Further functional studies will contribute to our understanding of NSUN2-intellectual disability syndrome and the mechanisms of action." (PMID 38643142, 2024).
invasive ductal breast carcinoma (1 paper, 2017). The most common type of invasive breast carcinoma, accounting for approximately 70% of breast carcinomas. "Analyzing the data in Oncomine database, we found that NSUN2 expression is upregulated in invasive ductal breast carcinomas, in comparison with the normal tissues, which agrees with the results of previous studies." (PMID 27447970, 2017).
lentivirus infection (1 paper, 2023). Virus diseases caused by the Lentivirus genus. "Depletion of NSUN2 in HepG2-NTCP is mediated by shRNA-expressing lentivirus infection." (PMID 38048324, 2023).
liver fibrosis (1 paper, 2025). "In this study, NSun2 deficiency was found to inhibit sinusoidal capillarization, alleviating liver fibrosis." (PMID 40355098, 2025). "However, the role of NSun2 and its mediated tsRNAs in liver fibrosis remains unclear." (PMID 40355098, 2025).
lung squamous cell carcinoma (1 paper, 2020). "No direct relation of NSUN2 and SLC39A8 with lung squamous cell carcinoma (LUSC) has been known so far." (PMID 32854705, 2020).
lymphoma (1 paper, 2021). A malignant (clonal) proliferation of B- lymphocytes or T- lymphocytes which involves the lymph nodes, bone marrow and/or extranodal sites. "Mechanistic studies have demonstrated that circ-NSUN2 can promote lymphoma progression by affecting Wnt pathways through the regulation of HMGA1." (PMID 35116058, 2021). "Mechanistic results suggest that circ-NSUN2, regulated by the transcription factor NRF1, can promote lymphoma progression by stabilizing the HMGA1-activated Wnt pathway." (PMID 35116058, 2021).
mastitis (1 paper, 2024). Inflammation of breast tissue during lactation or postpartum due to an obstructed duct or infection. "The m6A modification gene FTO showed significant effects on the expression of m6A and other RMRGs (such as NSUN2, CPSF2, and METTLE), indicating complex co-expression relationships among different RNA modifications in the regulation of bovine S. aureus mastitis." (PMID 38271969, 2024).
myocardial hypertrophy (1 paper, 2025). "We further cross-referenced the two gene lists, and 39 common genes most likely accounting for the regulatory effect of Nsun2 on cardiac hypertrophy were ultimately acquired." (PMID 39990213, 2025). "Moreover, we established an angiotensin II (AngII)-induced heart hypertrophy mouse model to further substantiate the role of cardiac Nsun2 in response to hypertrophic stresses." (PMID 39990213, 2025). "Aging can induce heart hypertrophy as a modest and long-term chronic stressor, and different regulators that address cardiac aging pressure demonstrate differential responsiveness 47; the same is likely true for METTL3 and Nsun2." (PMID 39990213, 2025). "Although knocking out Nsun2 greatly reduces myocardial hypertrophy, it exacerbates heart dysfunction rather than ameliorating or preserving heart function." (PMID 39990213, 2025).
parasitic infection (1 paper, 2024). "Malacid (Pyrimethamine), which significantly correlated with NSUN2 expression is mainly used for fungal and parasitic infection." (PMID 38277218, 2024).
poorly differentiated thyroid cancer (1 paper, 2023). "It was revealed that NSUN2 mRNA was markedly elevated in ATC compared with PTC, poorly differentiated thyroid cancer (PDTC), or normal thyroid tissue." (PMID 37983928, 2023).